ATF3 (activating transcription factor 3)
Diseases named in the same sentence as ATF3 in open-access papers (continued):
Sharing a sentence is not in itself a finding about the gene and the disease.
tumor (continued). "Multivariate analysis further revealed that ATF3 expression could be regarded as an independent predictor for OS in GCs (p = 0.032), as well as tumor size (p = 0.005)." (PMID 34728784, 2021). "Next, we assessed the impact of ATF3 on tumor metastasis in vivo." (PMID 34728784, 2021). "ATF3 was found to be expressed at low levels in multiple HCC tumor tissues." (PMID 33407456, 2021). "To validate the biological role of ATF3 in TSCCs through IFI6 and IFI27 in vivo, we first tested whether the inhibition of ATF3 promotes tumor growth of TSCCs in mice." (PMID 33539340, 2021). "The role of ATF3 in cancers has been extensively investigated and accumulated evidence has demonstrated that ATF3 can play tumor promoting or tumor suppressing functions depending on the type of tumor cell and the stromal context, and particularly, on the conditions of the cells as well." (PMID 33539340, 2021). "Importantly, analysis of the ATGC database showed that there was a significantly lower expression of ATF3 in tumor samples compared to normal tissues (P = 0.0037), which supports our findings." (PMID 33539340, 2021). "Therefore we conclude that ATF3 plays an anti-tumor function in TSCCs likely through the negative regulation of expression of its downstream targets IFI6 and IFI27." (PMID 33539340, 2021). "ATF3 displays conflicting functions in various diseases, and this may be due to the complicated tumor microenvironment, such as the community of genomically altered non-neoplastic cells, cancer cells, and various microorganisms." (PMID 33816467, 2021). "Considering that the anti-tumor effect of BTZ may be associated with the apoptotic pathway, we measured apoptosis activity after BTZ treatment and the effect of ATF3 on apoptosis." (PMID 34631548, 2021). "Thus, activation of Nrf2 as well as its down-stream target ATF3 will influence the cellular and cytokine dynamics in the tumor microenvironment." (PMID 35052581, 2021). "After adjusting for tumor purity, the results showed that ATF3 expression was significantly correlated with macrophage subpopulations, including tumor-associated macrophages (TAMs; CCL2, r = 0.245, P = 4.16e−06), M1 (NOS2, r = 0.137, P = 0.08e−02), and M2 (CD163, r = 0.141, P = 8.90e−03)." (PMID 33407456, 2021). "The activation of the tumor suppressive ATF3/GADD34 functional pathway and the inactivation of the AKT/β–catenin pathway was observed in general in all the experimental HCC environments of parental cell culture, isolated CSCs, and xenograft-tumors with CDCA8 depletion." (PMID 33801424, 2021). "For instance, ATF3 promotes tumor cell growth in skin, breast and lung cancer cells." (PMID 33539340, 2021). "In addition, we also detected substantially lower ATF3 mRNA in the livers of patients with HCC tumor tissues than in normal tissues using data from the Human Protein Atlas." (PMID 33407456, 2021). "A large number of studies have shown that Atf3 is a stress-inducible gene, but may also prevent apoptosis, stimulate cell proliferation, and tumor invasion." (PMID 33375092, 2020). "In HT29 cells, ATF3 has been shown to promote tumor growth, invasion, and migration." (PMID 32517689, 2020). "In addition, ATF3 upregulates the expression of some genes involved in tumor metastasis, including FN-1, Twist-related protein 1 (TWIST1), plasminogen activator inhibitor-1, urokinase-type plasminogen activator, caveolin-1, and Slug, in MCF10CA1a cells." (PMID 32922364, 2020). "In vivo, HDFs with high ATF3 expression reduced tumor formation." (PMID 32373541, 2020). "A decrease in Atf3 levels in the late stage cancer group may, together with the lack of hyperexcitability in this group, suggest an ongoing tumour-induced neurodegenerative change in this neuronal population." (PMID 33172040, 2020). "Tumour xenograft was used to evaluate the effect of ATF3 in vivo." (PMID 30117642, 2018).
tumor (continued). "ATF3 is known to function as a tumour suppressor in several cancer types." (PMID 29728077, 2018). "The results showed that overexpression of ATF3 could promote the growth of tumours (P < .05), while silence of ATF3 could inhibit the development of tumours (P < .05)." (PMID 30117642, 2018). "This study proposed that in cancer cells with β-catenin mutations, such as HCT116 cells, ATF3 transcription is constitutively activated through the β-catenin/TCF4 binding, but over-expressed ATF3 exhibits a tumor suppressive function by repressing cancer migration and invasion." (PMID 29966001, 2018). "These complexes can either activate or repress transcription depending on the composition of the complex (e.g., Jun-Jun, Jun-Fos, Jun-ATF3), the promoter type, and the cell type, and can therefore act as either tumor suppressors or oncogenes in various cancer types." (PMID 30348202, 2018). "On the other hand, qRT‐PCR was carried out to detect the level of ATF3 in tumour." (PMID 30117642, 2018). "ATF3 regulating HDC expressions in myeloid cells that contributed to the tumor growths may need to be validated for in vivo experiments in further studies." (PMID 28402947, 2017). "In different clinical stages, ATF3 staining score was much higher in the tumor tissues than in the adjacent normal tissues using paired t tests, which suggested that ATF3 expression increased significantly in the tumor tissue compared with the adjacent normal tissues." (PMID 28402947, 2017). "Thus, to fully characterize the function of ATF3 in tumor progression in CRC, we used an integrative strategy from ChIP-Seq, a larger database of gene profiling, molecular signatures with OS outcome and a TMA." (PMID 28402947, 2017). "ATF3 plays controversial roles both in oncogenesis and tumor suppression, which may be cell context dependent." (PMID 28402947, 2017). "However, some genes need to be further investigated in a tumor environment using ATF3 knockout mice in CRC models to characterize the impact, such as HDC." (PMID 28402947, 2017). "Moreover, the expression levels of ATF3 in CRC correlated with the expression of its target genes, such as CEACAM1, DUSP14, HDC, HLF and ULBP2, which are required for tumor cell invasion and proliferation and are robustly linked to poor prognosis in CRC." (PMID 28402947, 2017). "Finally, our in vivo experiments confirmed that the repeated peritumoral injection of ATF3-siRNA compared with the vehicle-treated controls effectively inhibited the growth of U373MG tumor xenografts in nude mice." (PMID 25872784, 2015). "In contrast to MMP2, maspin is one of the classic tumor suppressor genes, and the opposite changes observed for ATF3 versus maspin expression suggest that the function of ATF3 opposes that of maspin, with ATF3 having a tumor-promoting role that is opposite to that of maspin." (PMID 25872784, 2015). "ATF3 can induce cells to enter the cell cycle from the stationary phase, thus accelerating cell proliferation; this characteristic is important in the processes of invasion and migration and is significant for the prognosis for several types of tumor." (PMID 25872784, 2015). "Treatment of xenograft tumors with ATF3-siRNA began to show effects at the 16th day of treatment; tumor growth curves revealed that tumor growth in the ATF3-siRNA group was attenuated and the tumor volume was significantly reduced." (PMID 25872784, 2015). "Therefore, we propose a new model for ATF3 as a novel suppressor of tumor invasion and metastasis in ESCC." (PMID 25149542, 2014). "However, the mechanisms and transcriptional targets of ATF3 in tumor suppression remain largely undefined." (PMID 23533526, 2013).
tumor (continued). "Little is known about the specific pathways regulated by CREB5, however ATF3 is known to mediate repression of inflammatory signals, and may function as an oncogene or tumor suppressor depending on cell type and context." (PMID 23935999, 2013). "The effects of ATF3 expression in other systems are strongly context-dependent, and can include both apoptosis and growth stimulation, oncogenesis and tumor suppression." (PMID 21304988, 2011). "The biological function of ATF3 in vivo may rather highly rely on the microenvironment of a defined tumor entity." (PMID 21129190, 2010). "Moreover, in xenogenic mouse models, ATF3 knock-down promoted subcutaneous tumor growth and hepatic metastasis, as well as peritoneal carcinomatosis." (PMID 21129190, 2010). "In addition to its role in TGFβ-mediated Id1 repression, ATF3 also functions to suppress tumour growth." (PMID 20565867, 2010). "In normal tissues, ATF3 may promote both apoptosis and cell proliferation, while in neoplasms it has been identified as either an oncogene or as tumor suppressor, depending on tumor entity and grade." (PMID 21129190, 2010). "Thus, our finding from the standard IHC studies that the majority of tumor cells in the ATF3-induced murine tumors stained for both CK5 and CK8 was somewhat unusual." (PMID 18808719, 2008). "Thus, it is also possible that in both stromal and epithelial tumor components, ATF3 expression is part of an ongoing response to stressful conditions existing within the tumor microenvironment." (PMID 18808719, 2008). "Immunohistochemistry indicated that the outermost, basal layers of tumor cells (that is, furthest removed from the keratinaceous core) typically exhibited nuclear expression of the ATF3 transgene, and were enriched for dividing cells as shown by expression of the Ki67 proliferation marker." (PMID 18808719, 2008). "Furthermore, flow cytometric analysis of tumor-infiltrating lymphocytes revealed that Vin-induced increases in CD8+ T cell infiltration, as well as the proportions of GZMB+ and IFNγ+ CD8+ T cells, were abolished in both ATF3- and IL-24-deficient tumors." (PMID 40866941, 2025). "Interestingly, a similar induction of Atf3 is also observed in PSNs innervating the tumor." (PMID 38433844, 2024). "ATF3 was highly expressed when the organism encountered cancer cells as an adaptive‐response gene, which could induce apoptosis as a tumor suppressor or enhance BC cell tumorigenicity as an oncogene, contributing to epithelial‐to‐mesenchymal transition and metastasis." (PMID 35037412, 2022). "Whereas DC numbers and CD86 expression were comparable in tumors from these animals, the frequencies of active IFN-γ-expressing CD8+ T cells in the tumor (but not splenic) tissues were increased by ablation of ATF3 but decreased in response to the loss of CH25H in DCs regardless of the ATF3 status." (PMID 36333297, 2022). "Therefore, ATF3 could act as a potent modulator of immunotherapy by simultaneously affecting the tumor cell itself and the tumor microenvironment." (PMID 35738798, 2022). "Consequently, we speculated an important regulation axis in BCa that METTL1 promoted the processing of miR-760 in an m7G modification-dependent way and contributed to degradation of ATF3 mRNA, accelerating the tumor growth and metastasis eventually." (PMID 36396627, 2022). "Furthermore, western blot showed that inhibition of AKT1 reversed the effect of si-ATF3 to significantly increase Fas protein expression in tumor tissues, while to significantly decrease HLA-A, CCR5, FasL, HLA-E protein expression, which implied that the immune escape of cancer cells was diminished." (PMID 33794833, 2021).
tumor (continued). "Interestingly, Sample_15, a Gleason pattern 4 tumour, shows high enrichment for FOXA1, HOXB13 and CDX2, followed by Fra1/2, Atf3, JunB and AP-1 binding sites enriched in Gleason pattern 3 tumours, suggesting a transitionary state between the two regulatory states." (PMID 34911933, 2021). "In addition, ATF3 expression may be involved in the regulation of tumor-related and M1/M2 macrophages." (PMID 33407456, 2021). "We sought to determine whether ATF3 could exert an inhibitory effect on tumor growth in vivo." (PMID 33816467, 2021). "Therefore, we conclude that ATF3 plays an anti-tumor function in human TSCCs." (PMID 33539340, 2021). "Importantly, immunoblot from tumor tissues demonstrated that the suppression of ATF3/NOX4 axis in IFI6-overexpressed cells while this effect was reversed by phenformin treatment, validating the effect of IFI6-mediated OXPHOS efficiency on ATF3/NOX signaling pathway." (PMID 32727517, 2020). "However, the role of ATF3 in tumor stromal cells has been little explored so far." (PMID 32373541, 2020). "Although we cannot exclude the possibility that other factors induced in HDFs by pretreatment with CsA or phenformin are involved in inhibiting tumor cell growth, our results suggest that increased ATF3 expression in HDFs could potentially block tumor cell growth clinically." (PMID 32373541, 2020). "ATF3 may inhibit tumor formation by inducing cell cycle arrest and apoptosis." (PMID 30376856, 2018). "If ATF3 does act as a tumor suppressor, it may partially be due to the action of these compounds." (PMID 28402947, 2017). "In the tumors, ATF3 might induce cell apoptosis or improve cell survival depending on tumor types." (PMID 26917416, 2016). "We observed an enhanced migration behavior after ATF3 inhibition in vitro and hypothesized that loss of ATF3 function may also lead to an increased tumor metastasis in vivo, an aspect that has not been comprehensively investigated to date." (PMID 21129190, 2010). "Our work identifies HDAC7 as a molecular mediator that governs ATF3's functional plasticity through competitive cofactor recruitment, positioning HDAC7 inhibition as a therapeutic strategy to reactivate ATF3-mediated tumor suppression in CRC." (PMID 42157949, 2026). "The overexpression of ATF3 was shown to inhibit migration and the invasion of HCT116 cells, as well as reduce the size of mouse tumor xenografts." (PMID 39857803, 2025). "ATF3 suppresses expression of the enzyme cholesterol 25-hydroxylase (CH25H), which in turn promotes trogocytosis between CTLs and tumor cells, leading to T-cell dysfunction and tumor progression." (PMID 41019052, 2025). "Functional assays in ATF3-overexpressing and -knockdown HCC cell lines further confirm ATF3′s role as a tumor suppressor." (PMID 39996726, 2025). "ATF3-null CAR-T cells exhibit a reduction in exhaustion and apoptosis markers and improved anti-tumor reactivity due to increased expression of CH25H86." (PMID 39741180, 2025). "The reduction in CH25H expression is regulated by activating transcription factor-3 (ATF3), which is activated by numerous factors in the tumor microenvironment, such as hypoxia and nutrient deprivation." (PMID 39741180, 2025). "By repressing ATF3, VPS72 drives lipid biosynthesis and tumor progression, highlighting a novel mechanism of metabolic regulation in cancer." (PMID 40305746, 2025). "In xenograft models, ATF3 knockdown compromised the antitumor efficacy of AQB+CBPt, as evidenced by accelerated tumor growth and higher Ki-67 staining." (PMID 41353219, 2025).
tumor (continued). "mairei induces apoptosis of NSCLC cells, activating the ATF3–Hippo–YAP pathway in vivo, through a reduction in tumor volume and weight in nude mice, and that this was a result of upregulation of ATF3, p‐MOB1, and p‐YAP (Ser397)." (PMID 40895190, 2025). "The bar graphs indicated that the expression profiles of ATF3, CXCL2, RRAD, AREG, and CXCL8 in the C0 subtype were expressed at greater levels than in the remaining tumor cell subtypes." (PMID 40936936, 2025). "For a deeper understanding of the oncogenic mechanisms of the C0 MAFF+ tumor cell subtype, we analyzed the TFs within this subtype and identified the top five active TFs: KLF6, ATF3, JUN, FOS, and FOSB." (PMID 40936936, 2025). "Immunohistochemical staining of tumor tissues revealed a significant increase in Ki67 expression in the CCDC86 overexpression group, whereas ATF3 knockdown led to a decrease in Ki67 expression." (PMID 40837407, 2025). "C1 was primarily marked by the expression of genes related to tumor progression and migration (LPP and ATF3)." (PMID 40725006, 2025). "NU7441 treatment also decreased the protein expression of the tumor cell proliferation markers Ki‐67 and the TRIM24 downstream effector ATF3." (PMID 38828688, 2024). "ATF3, a member of the ATF/cAMP response element-binding (CREB) family of transcription factors, has recently been proposed by several studies as a new tumor suppressor factor." (PMID 39085957, 2024). "ATF3, a member of the cAMP responsive element-binding protein (CREB) family, has been found to be a tumor suppressor that inhibits proliferation and metastasis of HCC cells." (PMID 39749197, 2024). "Studies demonstrated enhanced tumor growth in cardiac remodeling models including TAC-operated mice, low-dose PE-induced HT mice, and ATF3-transgenic mice also reported increased periostin expression in cardiac tissues." (PMID 38279150, 2024). "Previous findings have shown that tumor cells increase PD-L1 expression through transcription factors such as IRF1/4, c-Myc, EGR1, c-Jun, HIF-1α, NF-κB, ATF3 and STAT3." (PMID 36854755, 2023). "Current evidence suggests that tumor-derived factors (TDFs) promote trogocytosis between CAR-expressing and tumor cells via activating transcription factor-3 (ATF3)." (PMID 37974170, 2023). "In a separate set of experiments, we aimed to examine the epistatic relationship between expression of ATF3 and CH25H in DCs and importance of this relationship for tumor growth." (PMID 36333297, 2022). "In all, these results suggest that ATF3-driven downregulation of CH25H in DCs plays an important function in evading anti-tumor immunity and in stimulation of tumor growth." (PMID 36333297, 2022). "Interestingly, previous reports have shown that ATF3 functions are context-dependent, and ATF3 may promote apoptosis or suppresses proapoptotic genes depending on whether it is activated in healthy versus tumor cells." (PMID 34941867, 2021). "Consistent with transcriptional profiling of the knockdown of CDCA8 expression, the protein levels of the ATF3 and GADD34 tumor suppressors were restored in the same condition." (PMID 33801424, 2021). "ATF3, a highly conserved transcription factor, was described as a principal target of EGR1 and discussed as a tumor suppressor and promoter." (PMID 34497759, 2021). "Our in vivo results strongly supported the in vitro data: after injection of ATF3-shRNA/AGS cells into nude mice, tumor growth and pulmonary metastasis were significantly increased compared with those in control mice." (PMID 34728784, 2021). "Activating transcription factor 3 (ATF3), a stress response gene, has been shown to play either tumor promoting or tumor suppressing functions depending on the type of tumor cell and the stromal context." (PMID 33539340, 2021).